KRT20 (keratin 20)
Diseases named in the same sentence as KRT20 in open-access papers (continued):
Sharing a sentence is not in itself a finding about the gene and the disease.
tumor (continued). "Transcriptional profiling classified the Ta tumours as luminal (high expression of luminal markers such as GATA3, PPARG, FOXA1 and XBP1 as well as differentiation markers such as UPK1A and KRT20) as well as non-aggressive (high expression of SKAP2, FABP4, MBNL2 and ID1)." (PMID 28916750, 2017). "KRT20 and UPK3 staining was remarkably inconsistent; a multitude of aberrant and heterogeneous expression patterns were observed for each marker, and, unlike that of the regulatory factors, KRT20 and UPK3 expression was hardly ever homogeneous in a tumour area 1 mm in diameter." (PMID 28195647, 2017).
cancer (69 papers, 2009 to 2025). A tumor composed of atypical neoplastic, often pleomorphic cells that invade other tissues. "In contrast, class 2 tumors showed a high expression of KRT20—a protein biomarker linked to carcinoma in situ and to differentiated luminal/umbrella cells." (PMID 34771699, 2021). "The expression level of Cytokeratin 20 (KRT20) is often helpful as a biomarker for identification and distinguishing between different types of cancer." (PMID 39329988, 2024). "Immunostaining with diagnostic markers such as cytokeratin 20 (CK20) and thyroid transcription factor 1 (TTF-1) can help differentiate these two cancers, but their sensitivity and specificity are limited." (PMID 38398178, 2024). "NSP3 largely resembles low aggressive luminal cancers, with high levels of KRT20, CDH1, and UPKSs, and affectation of the glycolytic pathway." (PMID 34771699, 2021). "Recently, single‐cell analysis of the transcriptome and epigenome also showed that KRT8, KRT18, CLDN4, KRT19, KRT20, etc. are highly expressed in CRCs,[12a] consistent with our results that these genes were highly expressed in cancer EPCs." (PMID 33898197, 2021). "To identify unequivocally in which tissue compartment the expression of TGFβ1 is upregulated, we performed fluorescence in situ hybridization (FISH) assay for TGFβ1 combined with cancer cell-specific (anti-Cytokeratin 20) staining." (PMID 34376784, 2021). "Cancers, including PCa, expressing cytokeratin 20 RNA can display a better prognosis than cancers with low cytokeratin transcript levels that belong to the basal-like subtype." (PMID 32947898, 2020). "In contrast, group IV* had relatively lower levels of KRT20 expression (the cancer cell marker) than group III* or group I+II." (PMID 33425745, 2020). "This study aimed to evaluate the clinical utility ofmonitoring cytokeratin 20 levels in peripheral blood and lymph nodes of patients withgastric cancer for detecting micrometastasis and predicting prognosis." (PMID 30827194, 2019). "We identified cell-adhesion/ECM genes that are down-regulated including KRT20 (cytokeratin 20) which is over-expressed in many epithelial carcinomas." (PMID 31797958, 2019). "KRT5 is a marker of stem or progenitor cells and can be found in basal-like carcinoma subtypes, often with squamous/sarcomatoid histological features, whereas KRT20, a marker of superficial umbrella cells, is enriched in luminal subtypes." (PMID 30380731, 2018). "The Ki-67 labelling index, defined as the percentage of cytokeratin-20-positive cancer cells with Ki-67-positive nuclei, was determined for n=207 cases." (PMID 22108518, 2012). "The expression spectrum of cytokeratin 20 in carcinomas resembles that observed in the corresponding normal epithelia of origin." (PMID 23272083, 2012). "Taken together, the decreased KRT20 activity due to propolis in early stage CRC tissues may reduce the chance of cancer worsening, metastasis, or recurrence." (PMID 37960147, 2023). "Cancer cells in tumors containing control, scrambled small guide (sgScramble) PDA cells demonstrated staining with fluorochrome-conjugated antibodies to KRT20, KRT19, and CXCL12, respectively, and CD3+ T cells were infrequent in the areas of the KRT20+ cancer cells." (PMID 35046049, 2022). "In addition, Keratin 20 negative patients have worse outcome compared to CA1 positive and Keratin 20 positive cancer patients." (PMID 22934030, 2012). "Moreover, the down regulation of keratin 20 in cancer cells following the co-culture with the CAFs may indicate the EMT induction." (PMID 22453032, 2012). "The cancer cell immunophenotype was cytokeratin 7 (CK7) (+), cytokeratin 20 (CK20) (−), estrogen receptor (ER) (+), Wilms’ tumor gene 1 (WT1) (−)." (PMID 40150013, 2025).
cancer (continued). "In a similar manner to the PAF1 knockdown, CDC73 or CTR9 knockdown inhibited cell proliferation, reduced the expression levels of most cancer stem cell marker genes including LGR5 and ID1, and increased those of KRT20 and MUCs." (PMID 38182897, 2024). "Crucially, expression of UBE2A mutants reduced the expression levels of most cancer stem cell marker genes including those of LGR5 and ID1 and increased those of KRT20 and MUCs." (PMID 38182897, 2024). "To verify the types of fibroblasts and myofibroblasts, we employed anti-human CD31, CDX2, Cytokeratin 20, and CD45 antibodies to stain endothelial cells of blood vessels, inflammatory cells and epithelial cells or cancer cells in the tissues of samples." (PMID 36463319, 2022). "Immunohistochemical analysis of 1882 CRC tissues from nine independent cohorts showed that 85% of tumors were positive for SATB2 and 97% for SATB2 and/or cytokeratin 20, suggesting that SATB2 is a highly sensitive marker to distinguish CRC from other cancers." (PMID 31492160, 2019). "The carcinomas are characterized with cytokeratin 7 (CK7), cytokeratin 20 (CK20), thyroid transcription factor 1 (TTF-1), estrogen receptor (ER) or prostate-specific antigen (PSA." (PMID 26695546, 2016). "Additionally, 18 CCC, 5 HGSC and 12 MC HSGs had OncoScore > 50, among these were candidate cancer biomarkers such as RNASET2 for CCC, AKR1B10 for HGSC, and KRT20 for MC." (PMID 40390000, 2025). "Keratin 20 (KRT20) is a well-recognized marker of differentiated intestinal cells that is notably absent in normal stem cells and suppressed in models of cancer initiation." (PMID 38472198, 2024). "On the other hand, the cancer cells showed negative IHC results for cytokeratin-20 (CK-20) and clathrin." (PMID 38115146, 2023). "However, upon ablation of LGR5+ cells, differentiated KRT20+ cancer cells can revert to LGR5+ cells and drive cancer regrowth." (PMID 31097693, 2019). "Out of 74 cancer specimens, 26 (35.1%) displayed a diffuse Krt7 immunoreactivity and an absence of Krt20/CDX2 expression." (PMID 29700411, 2018). "For example, several genes from the final part of the ranking, present specific clear information on MCC against the rest skin states as LGR5, POU4F1, SOSTDC1, KRT20, TGM3 and MYO15A genes, as their gene expression levels are opposite against to the other cancer-related skin states." (PMID 29750795, 2018). "For example, although MCC shows expression values contrary to the rest of skin states in the identified DEGs, there are genes like LGR5, POU4F1, SOSTDC1, KRT20 and MYO15A which are clearly postulated as differentiating genes in MCC diagnosing in comparison to other cancer-related skin states." (PMID 29750795, 2018). "To identify the tissue origin of the carcinoma, we use cytokeratin 7 (CK7), cytokeratin 20 (CK20), thyroid transcription factor 1 (TTF-1), estrogen receptor (ER) in female patients or prostate-specific antigen (PSA) in male patients as the minimal set of markers." (PMID 26695546, 2016). "Keratin 20 is typically expressed in cancers of the gastrointestinal tract and its negative expression can be used to exclude cancers of nonpulmonary origin." (PMID 25955027, 2015). "In some of the cases, keratin 20 can be negative, especially in carcinomas unrelated with MCV infection." (PMID 26607425, 2015). "We were able to examine LGR5 expression in 18 cases of adenocarcinoma, and consistent with the findings of Merlos-Suarez and colleagues, we report that in the majority of established carcinomas with a glandular structure, compartmentalization of LGR5 and KRT20 is present." (PMID 25728748, 2015). "This multimarker assay is based on the expression of three genetic markers: carcinoembryonic antigen (CEA), cytokeratin 20 (CK20), and/or cancer stem cells marker CD133 (CEA/CK/CD133) and was shown to be a useful tool for evaluation of CTC as a prognostic factor in PB of colorectal cancer patients." (PMID 25006584, 2014).
cancer (continued). "CTC presence was evaluated with real-time reverse transcription polymerase chain reaction assay (qPCR) based on the expression of three tumor genetic markers: carcinoembryonic antigen (CEA), cytokeratin 20 (CK20), and/or cancer stem cells marker CD133 (CEA/CK20/CD133)." (PMID 25006584, 2014).
adenocarcinoma (23 papers, 2008 to 2025). A common cancer characterized by the presence of malignant glandular cells. "The immunohistochemical markers most often employed in the work up of adenocarcinomas of different sites usually include Cytokeratin 20 (CK20) and CK7." (PMID 29721106, 2018). "Adenocarcinoma was immunohistochemically positive for pancytokeratin (AE1/AE3), cytokeratin 7 (CK7), cytokeratin 20 (CK20), and carcinoembryonic antigen (CEA)." (PMID 37927686, 2023). "Immunohistochemical staining was carried out to examine the expression of cytokeratin 7, cytokeratin 20, and caudal-related homeobox transcription factor 2 (CDX2) to determine the origin of the adenocarcinoma." (PMID 36532640, 2022). "We therefore analyzed LGR5 ISH and Ki67, KRT20 and CD44 IHC in 23 adenocarcinomas of all stages (pT1: n = 9, pT2: n = 3, pT3: n = 7, pT4: n = 4)." (PMID 25728748, 2015). "We analyzed the level of Ki67, KRT20 and CD44 expression in the adenocarcinomas (n = 23) by using a four grade semi-quantitative scoring system with 0 representing no staining and 3 representing the strongest staining." (PMID 25728748, 2015). "Cytokeratin 7 (CK7) and Cytokeratin 20 (CK20) are reliable and well-characterized immunohistochemical markers, and are usually helpful in distinguishing intestinal type and pancreaticobiliary type adenocarcinoma." (PMID 26603157, 2015). "The adenocarcinoma component was strongly positive for cytokeratin 7 and pancytokeratin, weakly positive for synaptophysin and CD56, and negative for carbonic anhydrase IX, CD99, CDX2, chromogranin, cytokeratin 20 and smooth muscle actin." (PMID 19523243, 2009). "The histological examination of the right hemicolectomy specimen revealed an adenocarcinoma in caecum staining positive for Cytokeratin 7 and Carcinoembryonic antigen and negative for Cytokeratin 20, CDX2 and Estrogen receptor." (PMID 18471290, 2008). "The final pathology report on the left corpus luteum cyst located a small focus of moderately differentiated adenocarcinoma in corpus luteum staining strongly positive for Cytokeratin 7 (CK7) and negative for Cytokeratin 20 (CK 20) suggesting a primary gastric or pancreatic carcinoma." (PMID 24708577, 2014).
infection (4 papers, 2016 to 2021). The state of being infected such as from the introduction of a foreign agent such as serum, vaccine, antigenic substance or organism. "Mature Krt20+ S cells are observed about 2 weeks after infection." (PMID 31597917, 2019). "We used qPCR to validate the SARS‐CoV‐2 infection‐dependent upregulation of the IFN‐γ target genes CXCL11 and IFIT3, as well as KRT20 and ACE2 and indeed confirmed an upregulation of these genes upon infection." (PMID 33544398, 2021). "Using the differentiation marker of the intestinal epithelium, cytokeratin 20 (CK20) and 16S rRNA probes we evidenced a productively infection in rare epithelial cells." (PMID 27025850, 2016). "Weak and patchy keratin 20 staining was also found six months after initial infection in UTI89HC mice, suggesting that these infection-induced changes to the host may be permanent." (PMID 30543708, 2018).
epithelial neoplasm (2 papers, 2019 to 2022). A benign or malignant neoplasm that arises from and is composed of epithelial cells. "In clinical terms, KRT20 is a well-established biomarker of various epithelial neoplasms, as it can be exploited for diagnosis, staging, and prognosis." (PMID 35327321, 2022). "In contrast, cytokeratin 20 expression is a routine test to detect epithelial neoplasms." (PMID 31027221, 2019).
KRT20 also shares sentences with these, for which no sentence is quoted: endometrial cancer (3 papers); mucinous adenocarcinoma (3); pancreatic adenocarcinoma (3); metastatic colorectal cancer (2); renal cell carcinoma (2); thyroid cancer (2); acinar carcinoma (1); ascending colon cancer (1); Barrett esophagus (1); bladder tumor (1); breast (1); breast tumor (1); cecal adenocarcinoma (1); cervical carcinoma (1); chronic kidney disease (1); colon (1); endometrial adenocarcinoma (1); esophageal carcinoma (1); Familial adenomatous polyposis (1); follicular carcinomas (1); gastrointestinal carcinoma (1); hepatocellular carcinoma (1); Hypertension (1); intestinal type adenocarcinoma (1); intrahepatic cholangiocarcinoma (1); kidney injury (1); large cell neuroendocrine carcinoma (1); liver cancer (1); neurological disease (1); oral cancer (1).
A further 17 diseases each share a sentence with KRT20 in 1 paper.